EGFR (epidermal growth factor receptor)
Diseases named in the same sentence as EGFR in open-access papers (continued):
Sharing a sentence is not in itself a finding about the gene and the disease.
tumor (continued). "Even in the absence of target-directing components such as EGFR peptide, selective accumulation of DNA in a tumor can be obtained via enhanced permeability and retention of tumor blood vessels." (PMID 29970866, 2018). "Surprisingly, addition of EGF at 50 ng/ml did not further improve viability and proliferation of the EGFR positive tumours in the fragments." (PMID 29861851, 2018). "They found while 90% of their tumor specimens had some EGFR staining and 53% had membranous staining, the EGFR staining alone was not of prognostic value." (PMID 29731973, 2018). "High concentrations of EGFR and IGFR suggest an opportunity for targeted inhibition, which could be a mechanism for disrupting tumor vessels on GBMs with a similar profile." (PMID 30050899, 2018). "Furthermore, the patient’s tumor harbored amplifications of BRAF, EGFR, MET, and CDK6, which provides a rationale for this tumor’s acquired resistance to the triple BRAF/MEK/CDK4&6 inhibitor treatment applied before sequencing." (PMID 30373609, 2018). "Given the EGFR overexpression in HNSCC, this disease is considered to be an EGFR-driven tumor." (PMID 29305574, 2018). "This study found that cell‐free DNA analysis reveals clinically important information during EGFR‐targeted therapy in non‐small‐cell lung cancer (NSCLC): At baseline, quantitative tumour‐derived cell‐free DNA levels in plasma provided prognostic information and correlated with tumour burden." (PMID 29848757, 2018). "Despite positive expression of EGFR by immunohistochemistry, the non-CE tumor did not demonstrate NIR fluorescence after cetuximab-IRDye800 administration." (PMID 29623552, 2018). "Taking advantage of this differential expression, we reason that in tumor cells where the EGFR expression is high, a low affinity EGFR ADC can achieve stable bivalent binding to the receptors, leading to efficient ADC internalization and killing of tumor cells." (PMID 30323890, 2018). "In vitro experiments demonstrated that overexpression of TUSC7/inhibition of miR-224 repressed cell proliferation and chemotherapy resistance via DESC1/EGFR/AKT pathway, and in vivo experiments demonstrated that overexpression of TUSC7 decreased tumor growth and chemotherapy resistance." (PMID 29530057, 2018). "Therefore, we re-evaluated EGFR as target in HNSCC in different cell lines and compared the properties of HNSCC cell lines with fresh tumor biopsies in order to validate the use of cell lines as representative of the clinical situation." (PMID 29989001, 2018). "Both EGFR (84.8%, 56/66) and SAE2 (91%, 60/66) were detected in most of the tumor fractions." (PMID 29855336, 2018). "The study also provides a clue about the communication between the EGFR/AR axis and MMP-9, which might be a crucial component of tumor dissemination and establishment at the metastatic sites." (PMID 30134822, 2018). "Epidermal growth factor receptor (EGFR) is a tyrosine kinase receptor that has been found to play an essential role in normal cell growth and differentiation and it is also involved in tumor proliferation and survival." (PMID 30274538, 2018). "In patients in the comparator arms, the incidence of post-progression anti-EGFR therapy was similar regardless of primary tumour location." (PMID 30013091, 2018). "Hence, we induced EGFR L858R expression in C57BL/6NTG(EGFR L858R) × TG(CC10‐RTTA) mice by doxycycline application and, after 8 weeks, we determined the tumor volume." (PMID 30220105, 2018). "Of these, prominent examples included amplifications targeting the epidermal growth factor receptor (EGFR) (7p11.2) and MYC (8q24.3) and deletions at 10q23.31, encompassing the PTEN tumour suppressor gene in cold tumours and JAK2 (9p24.1) amplifications in hot tumours." (PMID 30104673, 2018).
tumor (continued). "By showing that both EGFR and SAE2 are highly expressed in LADC, and that SAE2 expression correlates with patient’s poor outcomes, our data support their observations that SUMOylation is crucial for tumor progression." (PMID 29855336, 2018). "Positive HER-2, EGFR and VEGF expression can promote tumor growth." (PMID 29416785, 2018). "We also assessed the changes in in vivo EGFR expression level and glucose metabolism by anti-HER-1 therapy using immuno-PET agents 64Cu-PCTA-cetuximab and 18FDG-PET, respectively, which may provide new strategies in targeted tumor therapy." (PMID 30373221, 2018). "The data of ETS and DpR from three RCTs also favored the EGFR antibody irrespective of tumor location." (PMID 30296945, 2018). "In nontransformed cells, EGFR activation triggers inhibitory mechanisms including dephosphorylation and inactivation with inducible feedback inhibitors, acting as tumor suppressors." (PMID 30406002, 2018). "A number of NCs conjugated with Abs have been developed to target tumor which highly expressing a particular surface marker, such as human epidermal growth factor receptor 2 (HER2), epidermal growth factor receptor (EGFR), and vascular endothelial growth factor (VEGF)." (PMID 29718725, 2018). "Considering the relationship of EGFR with angiogenesis, we hypothesized that GDF15 secreted from chemotherapy damage to tumor cells could promote neo‐angiogenesis after TACE treatment, eventually leading to the residual tumor progression." (PMID 29383859, 2018). "EGFR is frequently amplified in GBM, contributing to tumor development and progression." (PMID 29991493, 2018). "EGFR has notably contributed to its early carcinogenesis from normal pancreatic epithelia, which transitions to neoplasms of pancreatic intraepithelial (PanIN) and finally, forming PDAC7." (PMID 29899472, 2018). "Ninety-six hours after transfection of ErbB3 SMARTpool siRNAs, tumor cells from CRC cultures were harvested and again probed for levels of EGFR activation, experiments which showed elevated levels of Trop2 and reduced levels of p-EGFR even when ErbB3 was incompletely suppressed." (PMID 29305574, 2018). "We and others found that DUSPs are some of the most robustly regulated downstream targets of EGFR/ErbB2 signaling and indeed both DUSP4 and DUSP6 independently serve key modulatory functions and might be candidate tumor suppressor genes." (PMID 29861842, 2018). "Furthermore, a crosstalk between the immunosuppressive microenvironment and the EGFR pathway activates several signal transduction cascades, including the MAPK, AKT, and PI3K pathways, and subsequent tumor growth and immunosuppression." (PMID 29658188, 2018). "Also, co-administration of EGFR inhibitor and AZ1366 provided better tumor control and improved survival in mice bearing orthotopic xenografts." (PMID 29458371, 2018). "In vitro, our data pointed to an involvement of IL-1 in tumor growth and the lack of response to EGFR interception." (PMID 30261609, 2018). "The first-line treatment of patients with metastatic NSCLC, without EGFR or ALK genomic tumor aberrations, is also in combination with pemetrexed and platinum chemotherapy." (PMID 30577797, 2018). "Moreover, there was a significant correlation between EGFR/MSI1 expression and grade of tumor differentiation (p = 0.02)." (PMID 30202417, 2018). "Indeed, differential amplification of RTKs, including EGFR, PDGFR, and MET was observed within tumor cells isolated from distinct regions of multifocal GBM in individual patients." (PMID 30573757, 2018). "Because the effects of miR-3140 on in vitro tumor cell growth were much greater than those of si-CDK2 and si-EGFR, concurrent downregulation of additional target genes may be necessary for the induction of miR-3140-mediated inhibition of tumor cell growth." (PMID 29540837, 2018). "Importantly, GNA significantly suppresses tumor growth in a lung patient-derived xenograft (PDX) model with FGFR fusion and low EGFR expression." (PMID 29449529, 2018).
tumor (continued). "Deregulation of EGFR and c-Met may trigger similar downstream signaling, such as Ras-MAPK and PI3-AKT for tumor progression." (PMID 30577605, 2018). "Despite the low affinity, RN765C is quite potent and has better anti-tumor activity compared to standard of care in multiple solid tumor models, including those that are non-responsive to naked EGFR antibody therapies or TKIs." (PMID 30323890, 2018). "Amongst these tumours, ROS1 rearrangements never overlap with ALK fusions, and rarely co-occurr with oncogenic EGFR mutations (0.5%; 1/220) or KRAS mutations (1.8%; 4/220)." (PMID 29455670, 2018). "Notably, this trial included patients with EGFR and ALK-driven tumours—a similar benefit was seen in these groups, as well across all PD-L1 expressions." (PMID 29904031, 2018). "A major reason being that, with the exception of growth factor receptor blocking antibodies (e.g. anti-EGFR mAbs), treatment with the majority of naked mAbs do not inhibit the growth in vitro and migration of tumours overexpressing the target antigens." (PMID 29731998, 2018). "The tumor signal intensity after ZEGFR:03115–IR700DX injection (6 μg) was calculated to be >6‐fold higher than the signal measured for ZTaq‐IR700DX, which confirmed the EGFR specificity of the affibody‐based conjugate in vivo." (PMID 29313975, 2018). "EGFR over-expression and 19 exon deletion can promote the expression of MMP-2 and MMP-9 by up-regulating CXCR4/CXCL12 signaling pathway, leading to the change of tumor biological characteristics such as higher proliferation, migration and invasion ability." (PMID 30037369, 2018). "The importance of PP2A in EGFR signaling is also illustrated by the finding that administering SMAPs, small molecule activators of PP2A, results in substantial inhibition of KRAS-driven tumor growth." (PMID 29455644, 2018). "In contrast, on EGFR overexpressing tumor cells, the high receptor density allows RN765C to establish stable bivalent binding leading to efficient ADC internalization and release of the payload to kill tumor cells." (PMID 30323890, 2018). "The over-expression of PD-L1, promoted by oncogenic and constitutively activated signals, including epidermal growth factor receptor (EGFR), protein kinase B (AKT) and Kirsten rat sarcoma viral oncogene homolog (KRAS) pathways, is responsible for an innate (tumor cell intrinsic) resistance." (PMID 30386337, 2018). "To test the hypothesis, we selected EGFR-positive HCT116 and HT29 cell lines as study models for investigating the molecular mechanism of CSCs that were considered responsible for tumor metastasis and recurrence." (PMID 30068339, 2018). "Using NSCLC patient tumor samples from multiple institutions, we characterized the immune gene expression signatures of CPI resistant EGFR and Nrf2 altered NSCLC genomic subsets and identified different potential mechanisms of CPI resistance in these genomic subsets." (PMID 30400822, 2018). "Chemokine levels were not related to histological tumor classification, but tumors with no expression of EGFR and p21 had significantly increased levels of CXCL8 and CXCL6, respectively." (PMID 29850390, 2018). "Furthermore, EGFR signaling through Akt increases the demand of EGFR mutant cells for fatty acid synthesis, resulting in the upregulation of FASN and rapid division of tumor cells." (PMID 29449326, 2018). "We previously identified EGFR immunoreactivity in ≥15% of tumor cell nuclei as a negative correlate of DFS in TNBC." (PMID 29883487, 2018). "To characterize the mutation status and gene expression levels of the cytokines IL-4 and IL-13, their receptors IL-4Rα, IL-13Rα1/2, and the oncogenes c-Met and EGFR, we performed exome and RNA-seq analysis on DIPG tissues (38 tumor exome, 26 normal exome, 28 tumor RNA, 18 normal RNA)." (PMID 29621254, 2018). "CA-siRNA(s) directed EGFR-1(50 nM) or EGFR-2 (50 nM) showed no robust tumor regression after 29 days of treatment." (PMID 29861465, 2018).
tumor (continued). "Preclinical studies have established the ability of T-cells targeting this unique, tumor-specific epitope to proliferate and release cytokines in response to stimulation with the mutant EGFRvIII antigen, but not wild-type EGFR." (PMID 30386740, 2018). "Studies demonstrate that both tumor subtypes arise from a common EGFR mutant tumor rather than from two distinct cancers, indicating that the tumor has adopted an entirely different cell fate." (PMID 29458371, 2018). "Staining of EGFR and HER3 showed strongest positivity on viable tumor cells." (PMID 29899472, 2018). "Pre-clinical studies also demonstrated greater anti-tumor activity with dual targeting of EGFR and IGFIR though clinical translation was not successful." (PMID 30412601, 2018). "However, patients with low levels of HIF-1α protein and a high content of EGFR protein in the tumor had a three-fold better survival compared to patients without such constellation regarding the protein level of HIF-1α and EGFR." (PMID 30513863, 2018). "Altogether, the data suggest that in HNSCC, full EGFR activation is dependent on the ErbB3-neuregulin-1 axis, a hierarchy that has not been previously demonstrated in any tumor type." (PMID 29305574, 2018). "Because the TKI resistant lines showed high phospho-EGFR levels and because of the crucial roles of YAP in supporting tumor survival in the presence of TKIs, we next aimed to identify whether YAP is an ideal target for combined inhibition with EGFR TKI." (PMID 29321482, 2018). "Collectively, our data show that mice bearing tumors expressing both EGFR and uPAR (i.e., RH30) had a greater effect on tumor growth over time, along with a higher number of complete responses to the toxin, compared to the TC-71 bearing mice that only expressed uPAR." (PMID 29552283, 2018). "The most common tumor targets are cell surface molecules, such as EGFR, HER2, Mesothelin, CD19, or CD20 whose cell membrane localization, and sometimes tumor-specific expression, or overexpression in comparison to healthy tissues, makes them suitable for antibody-based therapy." (PMID 29946318, 2018). "Anti-EGFR mAbs have advantages in the tumor shrinkage regardless of left- or right-sided tumors, which is important for conversion therapy." (PMID 30296945, 2018). "Furthermore, miR-133a-3p has been noted as a tumor suppressor miRNA downregulated in several cancers including HNSCC tumors and also known to target EGFR." (PMID 30289952, 2018). "There was a significant correlation between EGFR/MSI1 expression and tumor differentiation grade." (PMID 30202417, 2018). "In the tumor samples weak to moderate signals were detected which were restricted to the tumor cells whereas the surrounding stroma was negative for EGFR expression." (PMID 29989001, 2018). "They reported that subgroups of patients with HNSCC, who may achieve increased benefit from afatinib, were identified based on prespecified tumor biomarkers (i.e., HPV‐negative, EGFR amplification, low HER3 expression, and high PTEN expression." (PMID 29603584, 2018). "Adoptively transferred cells were shown to proliferate within the peripheral blood and traffic to intracranial tumor sites, exerting antitumor effects without any evidence of cross-toxicity with wild-type EGFR." (PMID 30386740, 2018). "Moreover, in our study we found a significant correlation between EGFR mRNA and HIF-1α mRNA expression in the tumor tissues as well as in the normal tissues." (PMID 30513863, 2018).
tumor (continued). "For example, externalized forms of nucleolin or a truncated form of estrogen receptor alpha (ER-α36) are overexpressed in cancer cells and interact with members of the human epidermal growth factor receptor (EGFR) family, providing a positive feedback loop that contributes to enhancing tumor growth." (PMID 30453567, 2018). "Mice were treated daily with either the EGFR BiTE® or the MEC14 negative control BiTE® one day after tumor implantation." (PMID 28837681, 2017). "KRAS is a key downstream effector of EGFR, and permanent activation of KRAS as a result of mutation causes cells to grow without exogenous stimulation and drives tumor initiation." (PMID 28077799, 2017). "The PDECX models without EGFR amplification but with high EGFR expression (IHC H score = 270~300) also responded strongly to theliatinib with tumor growth inhibition of 83~96%." (PMID 28881608, 2017). "Although molecular information was available for the tumor samples (IDH status, EGFR amplification, PTEN loss, MGMT promoter methylation), no discernable expression patterns were evident among these characteristics likely due to small sample sizes." (PMID 29142297, 2017). "Furthermore, EGFR and c-Jun were attenuated in the RHBDD1 knockdown and inactivated groups in animal tumor models." (PMID 28445956, 2017). "In this regard, it is worth noting that cetuximab has been shown to inhibit the growth of E6- and E7-expressing tumours grafted in NOD-SCID mice, thus offering further evidence of the combined effect of radiotherapy and anti-EGFR treatment in HPV-positive cancers." (PMID 31093349, 2017). "Overall, these oncogenic pathways cross-regulate each other and are regulated by EGFR, ERK, and Akt phosphorylation, forming an important network that enhances tumor cell activities such as evasion of apoptosis, immortalization, proliferation and metastasis in tumorigenesis." (PMID 28384287, 2017). "Recently, we determined that combined MET and EGFR inhibition was highly effective at abrogating tumor growth in patient-derived TNBC tumorgrafts and significantly decreased the variability in treatment response compared to monotherapy with MET or EGFR inhibitors." (PMID 28852500, 2017). "In one patient (No. 2) with multiple recurrences, the EGFR copy number increased in the recurring tumor." (PMID 28854970, 2017). "Members of the BAP complex exhibit tumor suppressor activity in tissue overexpressing the Yorkie (Yki) proto-oncogene, but not in tissue overexpressing epidermal growth factor receptor (EGFR)." (PMID 28754838, 2017). "Dermal toxicities commonly observed during therapy with mAbs targeting the wild-type EGFR should not be induced when targeting the tumor-restricted mutant EGFRvIII." (PMID 28596941, 2017). "In addition, PHS-based inhibition of EMT was attributable to the downregulation of the EGFR/JAK1/STAT3 signaling axis, as validated by immunoprecipitation assays and breast tumorigenesis mice models." (PMID 29100426, 2017). "It has to be mentioned that although our in vivo results obtained with transgenic mice imply that the functional stimulation of the EGFR-activity by HPV8E6 is essential for tumor induction, they do not prove it." (PMID 29176966, 2017). "Cross-talk between EGFR and EGFRvIII enables activating downstream signal pathways such as phosphoinositide 3-kinase, RTK, and phosphatase and tensin homolog, participating in tumor progression, angiogenesis, and treatment resistance." (PMID 29097933, 2017). "Even if a biopsy is performed, such a small tumor tissue sample cannot be assumed to reflect the entire tumor's Ki-67 index or EGFR expression." (PMID 28430583, 2017). "However, tumor volume and weight were smaller in mice with RPN2-silenced than in EGFR-silenced mice." (PMID 29069815, 2017). "To determine whether the results obtained with human tumor cell lines could be reproduced in murine tumors, we conducted transcriptional studies using F3II and D122 tumor cells (mouse cells with higher EGFR expression)." (PMID 29056908, 2017).